RNU6-551P (RNA, U6 small nuclear 551, pseudogene)
Gene: Small nuclear RNA gene on chromosome 4 (107,435,118 to 107,435,220, forward strand). Ensembl gene ENSG00000252470.
Homologues: Orthologues: chimpanzee U6 (99% identical), macaque U6 (90% identical), guinea pig U6 (71% identical), rat LOC120101963 (63% identical), mouse Gm55408 (61% identical), rabbit U6 (60% identical). Paralogues in human: RNU6-1094P (80% identical), RNU6-500P (80% identical), RNU6-992P (80% identical), RNU6-1091P (79% identical), RNU6-1243P (79% identical), RNU6-711P (79% identical), RNU6-776P (79% identical), RNU6-797P (79% identical), RNU6-1083P (78% identical), RNU6-1127P (78% identical), RNU6-1216P (78% identical), RNU6-1287P (78% identical), and 1289 more.